LIPC-AS1 (LIPC antisense RNA 1)
Gene: Long non-coding RNA gene on chromosome 15 (58,434,890 to 58,498,735, reverse strand). Ensembl gene ENSG00000259293.
Diseases named in the same sentence as LIPC-AS1 in open-access papers:
LIPC-AS1 is named in the same sentence as 4 diseases in open-access papers, as found by Europe PMC text mining. Sharing a sentence is not in itself a finding about the gene and the disease.
LIPC-AS1 shares sentences with these, for which no sentence is quoted: dyslipidemia (1 paper); Hyperglycemia (1); Obesity (1); type 2 diabetes (1).